SOX2 (SRY-box transcription factor 2)
Diseases named in the same sentence as SOX2 in open-access papers (continued):
Sharing a sentence is not in itself a finding about the gene and the disease.
glioma (continued). "In addition, PEDF maintains glioma stemness and self-renewal ability by activating Notch/Sox2 signaling axis and its silencing reduces the infiltration of GSCs and increases the survival of tumor bearing mice." (PMID 26880981, 2016). "Gene-set enrichment analysis shows SOX2 is involved in regulating “cell adhesion”, “biological adhesion”, “cell-cell signaling”, and “calcium ion binding” pathways, undercovering its key function as a driver of the glioma stem-like phenotype." (PMID 27669421, 2016). "Thus, tunicamycin inhibits the self-renewal of glioma-initiating cells partly through reducing Sox2 expression." (PMID 27119230, 2016). "Sox2 plays a critical role in the induction or maintenance of glioma ‘stemness’." (PMID 26755664, 2016). "Interestingly, most of these networks involved very well-known functions of SOX2 such as morphology determination, development and cellular proliferation and migration in glioma." (PMID 27669421, 2016). "Furthermore, we detected strong expression of the neural and glioma stem cell marker SOX2 in all our tested models." (PMID 27705917, 2016). "Moreover, the regulation of SOX2 through different miRNAs, including miRNA21 or miRNA145, has been described in glioma cells, with this axis having relevant functions in GSCs’ activity and in the clinic." (PMID 27822457, 2016). "Indeed, ectopic elevation of SOX2 increases the capacity of invasion and migration, in addition to cell proliferation and self-renewal activity in conventional glioma cell lines." (PMID 27822457, 2016). "Importantly, these results support a hierarchical model of glioma cells controlled by SOX2 expression, which brings up the idea to target SOX2 or to find downstream targetable genes as a strategy to eliminate GSCs and subsequently the tumor." (PMID 27822457, 2016). "Thus, Sox2 promotes glioma development, indicating that Sox2 would be an ideal target for glioblastoma therapy." (PMID 27119230, 2016). "Characterization of the resulting cell line (mGb4) by IF and FACS revealed that cells express CD15, CD133, CD44 stem cell markers together with SOX2 and OLIG2, two transcription factors associated with the maintenance of multipotency and proliferation of glioma multipotent cells." (PMID 26953813, 2016). "Interestingly, Mef was required for Sox2 and Id1 regulation in primary murine and human U87 glioma cells, both of which are important in maintaining the balance between differentiation and self-renewal." (PMID 27456282, 2016). "Attenuated S-phase entry was observed in human glioma cells upon inhibition of SOX2." (PMID 27791206, 2016). "Although triple treatment did not further reduce CD133+ surface population compared to dual treatments, it reduced SOX2 expression a widely used marker for repopulating cells in context of radiation resistance as well as Nestin another stem cell marker in glioma progression." (PMID 27183910, 2016). "However, we focused in the molecular circuitries controlled by SOX2 in GSCs, meanwhile they performed their study in an established glioma cell line." (PMID 27669421, 2016). "Thus, further investigation is warranted to characterize the expression of SOX2, OCT4, and NANOG in grade IV gliomas and examine potential associations with patient outcome and tumor aggressiveness." (PMID 26258069, 2015). "In our study, we utilized Oct4, Nanog and Sox2 transcription factors, which are linked to oncogenic transformation 15,16, and successfully reprogrammed two patient-derived GBM cell lines into CSC-like cells, which we term induced glioma stem cells (iGSCs)." (PMID 25787115, 2015). "This study emphasizes the utility of Sox2 as a marker of neural stem/progenitor cells, and supports the hypothesis that these cells respond to non-glial neoplasms of the CNS of epithelial and hematopoietic origin." (PMID 25713758, 2015). "In addition, in vitro studies of glioma cell lines in conditions that promote stemness and tumoursphere formation increased expression of SOX2, OCT4 and NANOG." (PMID 26580604, 2015).
glioma (continued). "Moreover, we show that PEDF maintains glioma stemness and self-renewal ability by activating Notch/Sox2 signaling, and silencing of PEDF decreases the infiltration of GSCs and increases the survival of tumor-bearing mice." (PMID 25992628, 2015). "SOX2 expression is very minimal in the adult brain and is only limited to stem cells and progenitor cells, thus emphasizing the possibility of SOX2, as a potential therapeutic target for grade IV gliomas." (PMID 26258069, 2015). "Taken above studies together, it suggested that BPA exposure might activate Shh to down-regulate Sox2 and Pax6 potentially for glioma and medulloblastoma brain cancers." (PMID 25051057, 2014). "Moreover SOX2 overexpression in the SOX2-negative glioma cell line U-87 resulted in a significant increase in the number of migratory and invasive cells." (PMID 25114775, 2014). "Similarly, SOX4 and POU class 5 homeobox 1 (OCT-4) proteins were also shown to activate SOX2 transcription in glioma initiating cells." (PMID 23613880, 2013). "Notably, Bmi-1 and Sox2 were upregulated at therapeutic concentrations of melatonin in the glioma cell line." (PMID 24137328, 2013). "The transcription of Nestin, along with the transcription of two other genes that are important to nervous system development (Bmi-1 and Sox2), were used as markers of cell proliferation to evaluate the role of melatonin on glioma cell differentiation and proliferation." (PMID 24137328, 2013). "However, both of these ABC transporters are transcriptionally regulated by SOX2, which is elevated in glioma stem cells by ID4-mediated suppression of miR-9*." (PMID 24358977, 2013). "Sox2 plays a critical role in both neural stem cells and CSCs and may serve as a novel and potential biomarker for CSCs in gliomas." (PMID 23554769, 2012). "As a stemness gene, Sox2 plays an essential role in maintaining the stemness property of glioma-initiating cells (GICs), where the expression of Sox2 gene could be induced by autocrine TGF-β through its target gene, Sox4." (PMID 23443092, 2012). "Next we were interested whether knockdown of SOX2 affects the differentiation status of the glioma cells besides the attenuated S-phase entry." (PMID 22070920, 2011). "In the present study we sought to elucidate the role of SOX2 in glioma malignancy." (PMID 22070920, 2011). "Because we observed remarkable morphological changes and a remodeling of the actin cytoskeleton of the glioma cells with knockdown of SOX2 we hypothesized that the migratory capacity of these cells might be affected." (PMID 22070920, 2011). "Hence, we suggest that RNAi of SOX2 in U343-MG and U373-MG glioma cells impairs cyclinD1 transcription and affects proliferation in the same way." (PMID 22070920, 2011). "Thus, it is possible that the transcription factors Sox2, Oct4 and Nanog that regulate self-renewal and pluripotency of stem cells have similar regulatory functions in gliomas." (PMID 21483788, 2011). "Further analysis revealed that the loss of invasive proteolysis-dependent migration capacity of glioma cells with knockdown of SOX2 could be compensated by a shift to amoeboid migration governed by increased RhoA/ROCK2 signaling." (PMID 22070920, 2011). "Furthermore, we observed that ectopic Sox2 expression was sufficient to induce invasion and migration of glioma cells, and knockdown experiments demonstrated that Sox2 was essential for maintaining these properties." (PMID 22069467, 2011). "In our previous work we detected SOX2 in glioma cells and glioblastoma specimens." (PMID 22070920, 2011). "Western blot analysis five days after transduction revealed an impaired expression of cyclinD1 in U343-MG and U373-MG glioma cells with knockdown of SOX2 when compared to cells transduced with the shLuc control vector, whereas cyclinE levels remained unaffected." (PMID 22070920, 2011). "However, it became clear that the glioma cells with knockdown of SOX2 had the capacity to migrate into the brain tissue." (PMID 22070920, 2011).
glioma (continued). "Thus, knockdown of SOX2 expression impaired proteolytic invasion of U343-MG and U373-MG glioma cells through collagen matrices." (PMID 22070920, 2011). "In fact, we found that RNAi of SOX2 attenuated proliferation of U343-MG and U373-MG glioma cells." (PMID 22070920, 2011). "However, in contrast to NSCs glioma cells co-express neural proteins together with pluripotent stem cell markers, including the transcription factors Oct4, Sox2, Nanog and Klf4." (PMID 21483788, 2011). "Although earlier studies have indicated the independent expression of Sox2 and Twist1 in different cancers including glioma, the functional relationship of Sox2 and Twist1 together in GSC remains unknown." (PMID 22184289, 2011). "In keeping with these findings, misexpression of Sox3 has previously been demonstrated to cause oncogenic transformation of embryonic fibroblasts whereas microRNA-mediated suppression of Sox2 decreases the capacity of glioma cells to contribute to tumor growth." (PMID 21483788, 2011). "Interestingly, Western blot analyses at two different time points 3 and 5 days after transduction revealed a marked reduction of FAK phosphorylation at Y397 for the SOX2-depleted glioma cells when compared to shLuc-transduced controls." (PMID 22070920, 2011). "The abundant and glioma-restricted overexpression of SOX2 and the generation of SOX2-specific and tumour-reactive CTLs may recommend this antigen as target for T-cell-based immunotherapy of glioma." (PMID 17375044, 2007). "Furthermore, the expression of SOX2 showed a strong positive correlation with ZFHX4 in glioma." (PMID 41458623, 2025). "We detected genes upregulated in PBT030 cells, such as SOX2, MYCN, NOS2, RUNX2, and VEGFA, while PBT147 cells upregulated level of PTEN, STAT6, CA9 and TLR2, demonstrating differences among PBT cell lines, which can be explained by various driving mutations and heterogeneity in glioma lines." (PMID 38449858, 2024). "Another study observed that upregulation of SOX2 expression in glioma stem cells was able to reduce the expression level of γH2AX after radiotherapy, which by further analysis was found to be possibly related to the involvement of SOX2 in the Homologous Recombination (HR) repair pathway." (PMID 37213675, 2023). "Thus, we examined SOX2 mRNA and protein levels in the brain tissues of patients with gliomas." (PMID 37058447, 2023). "However, the posttranscriptional regulation of SOX2 by long noncoding RNAs in gliomas remains unclear." (PMID 37063420, 2023). "Furthermore, it has been reported that SOX2 could contribute to the self-renewal and proliferation of glioma-initiating cells, which are important for the initiation, propagation, and recurrence of glioma." (PMID 37047365, 2023). "Therefore, we decided to decipher the potential mechanism by which the GSCAR/miR-6760-5p/SRSF1 axis and GSCAR/DHX9-IGF2BP2/SOX2 feedback loop promote glioma progression, which may provide new therapeutic targets for glioma in the future." (PMID 37063420, 2023). "However, there are few studies on the relationship between HIF2α and Sox2 in glioma, let alone whether these two factors can induce glioma cell dedifferentiation under hypoxic conditions." (PMID 34976166, 2022). "Therefore, we performed a series of experiments to verify whether HIF1α, HIF2α and Sox2 regulated glioma cell dedifferentiation under hypoxic conditions." (PMID 34976166, 2022). "In glioma therapy, the miR-145/SOX2-Wnt/β-catenin axis plays a key role in DMC-mediated glioma stem cell (GSC) inhibition, and upregulation of miR-145 can effectively enhance the effect of DMC against GSC; therefore, this may be a new therapeutic target for GSC resistance." (PMID 35684449, 2022).
glioma (continued). "These factors are represented by SRY-Box Transcription Factor 2 (Sox2) and octamer-binding transcription factor 4 (Oct4) whose activation promotes the suppression of both innate and adaptive immune responses maintaining glioma cell stemness and tumor-propagating potential." (PMID 35311140, 2022). "Moreover, previous studies showed that METTL3 could elevate the stability of SOX2 by increasing its m6A level, thus contributing to the progression of glioma and colorectal cancer." (PMID 35467477, 2022). "In addition, lncRNA NEAT1 could promote SOX2 expression by inhibiting miR-132, thus promoting glioma development." (PMID 35300348, 2022). "Therefore, we wondered whether these factors could induce the formation of GSCs and found that Sox2 was highly expressed in glioma according to The Cancer Genome Atlas (TCGA) database and promoted the dedifferentiation process in a hypoxic environment." (PMID 34976166, 2022). "However, the results from the TCGA databases showed that Sox2 was highly expressed in glioma tissues and that the expression pattern exhibited a large difference between tumor and normal tissues, so we focused on detecting the influence of Sox2 on the dedifferentiation process." (PMID 34976166, 2022). "NANOG, SOX2 and POU5F1, three stemness-associated genes that are part of the FA-BSA-NP delivery system, could facilitate autophagy inhibition and chemotherapy efficacy in glioma therapy." (PMID 34475426, 2021). "Therefore, glioma stem cell-related vaccines targeting SOX2 and other glioma stem cell-related genes may provide a new regimen for active immunotherapy." (PMID 34630121, 2021). "SOX2 / SOX21 axis could function as a tumor suppressor during glioma genesis." (PMID 32388501, 2020). "Moreover, PTPRZ1 and SOX2 were significantly overexpressed in glioma cells and could therefore be considered as useful markers to estimate the tumor cell purity in bulk glioma tissues." (PMID 34692159, 2020). "Interestingly, we found that B7-H6 was coexpressed with Sox2 in glioma cells." (PMID 32322592, 2020). "Similarly, SOX2 expression levels were increased in higher grade gliomas compared with Grade I samples, consistent with the expression trend of MRPs, and the expression level was higher in the glioma cell lines when compared with NHA." (PMID 32439916, 2020). "Besides, SOX2+ tumor cells were enriched in gliomas that could relapse following radiation therapy or chemotherapy with TMZ, and it was evinced that glioma cell population with CD133+ (an important marker for GSC) had higher levels of SOX2 expression." (PMID 30517668, 2020). "Additionally, they discovered human leukocyte antigen (HLA)-A*0201-restricted SOX2-derived peptides that were capable of eliciting glioma-reactive CD8+ cytotoxic T lymphocyte (CTLs) responses that could destroy glioma cells." (PMID 30517668, 2020). "SOX2 expression of recurrent gliomas remains unknown so far." (PMID 31718604, 2019). "Thus, it will be worthwhile to investigate whether the circDENND2A/miR-625-5p pathway participates in hypoxia-induced stemness and EMT in glioma by regulating SOX2." (PMID 30988674, 2019). "Therefore, decreased SOX2 expression in recurrent glioma might probably due to the tumor transformation from the proneural subtype into the mesenchymal subtype." (PMID 31718604, 2019). "Therefore, through targeting miR-132, NEAT1 could indirectly regulate SOX2’s expression, thus affecting glioma progression." (PMID 30053878, 2018). "NEAT1 and SOX2 knockdown could restrain the viability and invasiveness of glioma cells." (PMID 30053878, 2018). "Additionally, our functional data suggest the utility of high ALDH3A1 expression as a putative diagnostic marker for stemness in glioma as indicated by reduced expression of CD133, Nestin and Sox2 as well as diminished clonogenicity in response to ALDH3A1 inhibition." (PMID 29854309, 2018). "Therefore, SOX2 positively affected cancer development in glioma." (PMID 30053878, 2018).
glioma (continued). "Down-regulation of SOX2 could effectively suppress the development of glioma." (PMID 30053878, 2018). "In addition to NEAT1, SOX2 was also over-expressed in glioma as well as other human tumors." (PMID 30053878, 2018). "Here, we uncovered that NEAT1 could modulate SOX2 expression in glioma by sponging miR-132." (PMID 30053878, 2018). "Moreover, it has been reported that HIF-2α may regulate the expression of Sox-2, Oct4, and Nanog, and in glioma cells HIF-2α expression was observed only in the CSC population." (PMID 28468237, 2017). "In addition, Twist1, an EMT inducer, was recently shown to co-regulate glioma stemness with Sox2." (PMID 29228694, 2017). "RNA analysis of GSCs also revealed increased expression of mesenchymal/stemness markers (Fibronectin, YLK-4, CD44 and Sox2) following treatment with IL-17, suggesting that IL-17 may play a role in altering the plasticity of gliomas by inducing ‘stemness’ or enhancing glial-mesenchymal transition." (PMID 26755664, 2016). "However, SOX2 was expressed at relatively high level in differentiated L0125 cells, suggesting that its expression in glioma cells may have different, stemness-unrelated functions." (PMID 27934912, 2016). "Moreover, TGF-beta induced expression of SOX2 was mediated by SOX4 in glioma-initiating cells." (PMID 24828201, 2014). "Interestingly, both Sox2 and Olig2 have been ascribed important roles in maintaining self-renewing stem cells in the CNS and this activity appears, at least in part, to be conserved in gliomas." (PMID 21483788, 2011). "Immunocytochemistry showed that Sox2 and Bmi1, which are necessary for the normal functioning of both embryonic stem cells and neural stem cells, were expressed by a majority of cells in the low- and high-grade gliomas cultures studied (10/10 and 6/6 cultures, respectively)." (PMID 21297991, 2011). "Thus, rather than reflecting the formation of cells of endodermal or mesodermal lineages, it is conceivable that the mixed cellular phenotype in high grade gliomas results from deregulated gene expression, perhaps involving the activity of Sox2, Oct4 and Nanog." (PMID 21483788, 2011). "Interestingly, upon knockdown of SOX2 the expression of the stem cell markers Nestin and Oct4 was decreased in U343-MG and U373-MG glioma cells supporting the view that SOX2 preserves a more undifferentiated cell phenotype as previously observed in neural stem cells." (PMID 22070920, 2011). "Thus, knockdown of SOX2 obviously impaired the G1 to S-phase transition of glioma cells." (PMID 22070920, 2011). "Hence, RNAi of SOX2 induces an increased RhoA signaling in U343-MG and U373-MG glioma cells." (PMID 22070920, 2011). "Knocking out ZEB1 in GBM cells inhibits the expression of key glioma stem cell markers, including CD133, SOX2, and OLIG2, thereby suppressing GSC initiation, invasion, and chemoresistance." (PMID 41141394, 2026). "In glioma, high ELF4 expression up-regulates the SRY-box transcription factor 2 (SOX2) expression, enhancing cancer stem cells' features and promoting tumor occurrence." (PMID 40083328, 2025). "By elucidating this complete ZFHX4-AS1/ZFHX4/SOX2/JAK-STAT pathway, our work moves beyond a simple linear model to provide a deeper understanding of glioma pathogenesis, identifying a more refined set of potential therapeutic targets for intervention." (PMID 41458623, 2025). "From the figure, it is evident that in both groups of gliomas, the NOTCH1 and SOX2 genes were most affected by changes." (PMID 40679044, 2025). "In TCGA glioma samples, USP14 showed positive correlation with CD44 and ALDH1A3, and inverse correlation with PN markers, SOX2 and OLIG2." (PMID 39990235, 2025). "At the same time, eckol was observed to reduce the expression of glioma stem cell markers such as CD133, nestin and Musashi-1, Sox2, Notch2, and β-catenin." (PMID 40559213, 2025).